IL18 (interleukin 18)
Diseases named in the same sentence as IL18 in open-access papers (continued):
Sharing a sentence is not in itself a finding about the gene and the disease.
atherosclerosis (continued). "IL-18 can trigger atherosclerosis-relevant IFNγ expression even in the absence of T cells, as the administration of recombinant IL-18 to lymphocyte-deficient SCID mice led to increased lesion size accompanied by elevated IFNγ levels in the circulation." (PMID 33562334, 2021). "Similarly, IL-18 has been found to promote the development of atherosclerosis by promoting lipoprotein oxidation, macrophage-derived foam cell formation, and immune cell activation." (PMID 35096837, 2021). "Additionally, we proved that IL-18, together with the directly dependent signaling pathways is crucial for atherosclerosis, and can be considered a good candidate for a biomarker of atherosclerosis." (PMID 33202974, 2020). "In addition to its role in autoimmune diseases, IL-18 contributes to the process of atherosclerosis and, therefore, by inference to aging." (PMID 32297262, 2020). "The adaptive immune response is related to tumor necrosis factor (TNF) produced by T cells or type I interferon (IFN), and some inflammatory factors, such as IL-12, IL-23, and IL-18, can produce proplaque factors and accelerate the progression of atherosclerosis." (PMID 32733941, 2020). "The positive correlation between M-CSF and IL-18 suggests that they may have a synergistic effect on atherosclerosis in hemodialysis." (PMID 31419967, 2019). "IL-1β represents the tip of the iceberg; there are several other potential inflammatory mediators that could be directly targeted to halt atherosclerosis progression, such as by directly targeting the inflammasome, IL-1α, IL-6, IL-18, and IL-33, among others." (PMID 31672136, 2019). "SFA or cholesterol loading of macrophages is known to induce robust ER stress and mitochondrial oxidative stress, upstream of NLRP3 inflammasome activation and IL-1β and IL-18 secretion, resulting in an inflammatory response that drives atherosclerosis progression." (PMID 31422082, 2019). "Improved intensity of atherosclerosis may be related to changes in IL-18/IL-18-BP balance, and elevated free IL-18 levels have been identified in the circulation of disease states." (PMID 29485097, 2018). "Higher expression of NLRP3, AIM2, and ASC could give rise to IL-1β and IL-18 secretion, promoting atherosclerosis and further destabilizing atherosclerotic plaques, which indicates their importance in cardiovascular disease pathogenesis." (PMID 30555415, 2018). "In addition, Skoura and colleagues proved that S1PR2 expressed in macrophages of atherosclerotic plaque regulates inflammatory cytokine secretion (IL-1β, IL-18) and promotes atherosclerosis." (PMID 27965665, 2016). "In addition, the S1P receptor S1P2 regulates vascular inflammation and atherosclerosis by inducing the release of inflammatory cytokines IL-1β and IL-18 and retaining macrophages in plaques." (PMID 27711202, 2016). "It is difficult to ascertain if IL-18 is a good indicator of severity of atherosclerosis, but it seems to be a good indicator of its clinical complications among patient suffering from CKD, without diabetes mellitus, and with AMI in the year prior to the enrolment." (PMID 26669254, 2015). "In contrast to the atherogeneic effects of IL-18, IL-18BP is an endogenous modulator of IL-18 that prevents fatty streak development and slows progression of advanced atherosclerotic plaques in murine models of atherosclerosis." (PMID 25699211, 2015). "Taken together, physical activity and/or physical fitness may reduce serum IL-18 levels resulting in protective effect on atherosclerosis." (PMID 24349077, 2013). "Moreover, IL-18 is up-regulated in T2DM patients and has been linked to increased secondary renal failure and atherosclerosis." (PMID 23087690, 2012).
atherosclerosis (continued). "We hypothesized that circulating levels of IL-18 may enhance atherosclerosis-prone conditions in patients with MetS." (PMID 21251304, 2011). "Interestingly, IL-18-mediated increase of atherosclerosis is accompanied by elevation of SR-PSOX/CXCL16 expression." (PMID 21042583, 2010). "Additionally, neutrophils can participate in NETosis, resulting in the release of neutrophil extracellular traps (NETs) that enhance macrophage activation and the secretion of proinflammatory cytokines, including IL-1β and IL-18, thereby accelerating the progression of atherosclerosis." (PMID 40643541, 2025). "Therefore, we decided to address the role of IL18 in Tfh cell formation in atherosclerosis." (PMID 38381113, 2024). "Therefore, IL-18 SNPs can be the markers for IR and atherosclerosis." (PMID 36984867, 2023). "Studies have revealed that TMAO promoted vascular endothelial cell inflammation and advanced atherosclerosis by increasing the expression of the nuclear-factor kappa B (NF-κB), nucleotide-binding oligomerization domain-like receptor family pyrin domain containing 3, IL-1β, and IL-18." (PMID 35242275, 2022). "Indeed, recombinant IL-18 administration to Apoe−/− mice promoted atherosclerosis development in an IFNγ-dependent manner, while its neutralization by the natural inhibitor IL-18 binding protein (IL-18BP) or genetic knockout of IL-18 significantly reduced disease progression." (PMID 33562334, 2021). "Thus, IL-18 has interest as a target in inhibiting atherosclerosis." (PMID 33924019, 2021). "Furthermore, aside from inducing IFN-γ, IL-18 can also induce expression of TNF-α and synthesis of IL-10, cytokines that can inhibit the inflammatory process, leading to the instability of atherosclerosis plaques and formation of thromboses, a main risk factor for stroke." (PMID 31525735, 2019). "Blocking the effects of IL‐18 reduces the atherosclerotic lesion size and induces a switch to a stable plaque phenotype, whereas both endogenous and exogenous IL‐18 accelerated atherosclerosis development 31, 32, suggesting IL‐37 may play a protective role in atherosclerosis via inhibiting IL‐18." (PMID 28548248, 2017). "Therefore, the increase of serum IL-18 concentration in PCOS patients might be due to the presence of subclinical atherosclerosis in these women." (PMID 21244650, 2011). "For example, in a mouse model of atherosclerosis induced by a HFD, the protein levels of NLRP3, ASC, GSDMD-N, IL-1β, and IL-18 were significantly elevated; GSDMD-mediated pyroptosis then accelerated the progression of atherosclerosis." (PMID 41194915, 2025). "In late-stage atherosclerosis, NLRP3 inflammasomes induce macrophage cell death by pyroptosis, releasing IL-1β, IL-18, and inflammatory lipids, which increase plaque size and vulnerability to vessel rupture." (PMID 38335214, 2024). "Antigen exposure and IL-12 and IL-18 from macrophages induce Th1 differentiation and IFN-γ secretion, promoting atherosclerosis via EC junction disruption, foam-cell formation, matrix degradation, and plaque destabilization." (PMID 39113913, 2024). "IL18 and TRAF6 nodes in the macrophage autophagy network regulate inflammatory processes and plaque instability in atherosclerosis." (PMID 38984353, 2024). "A notable increase in serum IL‐1β, IL‐18, and IL‐6 levels was observed in atherosclerosis mice, and METTL3 knockdown in atherosclerosis mice significantly decreased these inflammatory markers." (PMID 39432244, 2024). "This review identified CHI3L1, CD36, LEPR, RETN, IL-18, RBP-4, and RARRES2 genes as the potential genetic markers of IR and atherosclerosis in T2DM patients with CAD." (PMID 36984867, 2023).
atherosclerosis (continued). "We noted a significant upregulation between MYD88 and CCL20 (G60); IFNβ (G90); NF-kB, IL18 (G120); NF-kB, CCR2, IL1b, IL18 (GF120); and CCR2 (GR120) in the thoracic aorta during the inflammatory process of atherosclerosis." (PMID 37298199, 2023). "This review focuses on the link between IR, T2DM, atherosclerosis, CAD, and the potential genetic markers CHI3L1, CD36, LEPR, RETN, IL-18, RBP-4, and RARRES2 genes." (PMID 36984867, 2023). "Clinical research on the signaling pathways leading to atherosclerosis has suggested that components of NETosis evoke NLRP3 inflammasome activation, which releases the proinflammatory cytokines IL-1β and IL-18." (PMID 36851139, 2023). "The eight major genes upregulated in the carotid vessels (IL18, PDGFRA, IL17, LOX1, TLR4, MYF5, IL1B, and PDPN) were intimately involved in the pathologic progression of atherosclerosis and NIH." (PMID 35531433, 2022). "Increased fatty liver-induced proinflammatory cytokines such as IL-1β, IL-18, and TNF-α can affect the development of atherosclerosis." (PMID 36364718, 2022). "Studies conducted in the early 2000s examined the effects of IL-1β and IL-18, downstream cytokines of the NLRP3 inflammasome, on atherosclerosis in mice." (PMID 36082127, 2022). "Together, these results suggest that the signature of IL-32 isoforms together with IL-18, VEGF-A, IFNβ, TRAIL and IL-1β correlate with subclinical atherosclerosis in HIV infection." (PMID 33936102, 2021). "Therefore, IFN-γ induction may explain the critical role of IL-18 in atherosclerosis." (PMID 32823917, 2020). "Hence, induction of IFN-γ may explain the critical role of IL-18 in atherosclerosis." (PMID 30400655, 2018). "In experimental studies the infusion of IFN-γ, IL-12, or IL-18 all increase atherosclerosis, whereas the infusion of antibodies to CD50L and oxLDL reduce atherosclerosis." (PMID 30538987, 2018). "In 2001, researchers found that IL-18-binding protein, an IL-18 inhibitor, could not only attenuate the progress of plaque formation in the aorta but also decrease lymphocyte infiltration and lipid content in the lesion, thus exerting protective effects against atherosclerosis on Apoe−/− mice." (PMID 29850631, 2018). "The laboratory indices of microinflammation include elevated blood levels of CRP and some cytokines, mainly IL-6, IL-18, IL-10, and TNF-alpha, which correlated with acceleration of atherosclerosis." (PMID 26236736, 2015). "Thus, serum IL-18 levels might be important factor and predictor in the process of atherosclerosis." (PMID 24349077, 2013). "Chronic elevated levels of IL-18 may lead to a persistently increased expression of IL-18 inducible cytokines downstream of the NF-κB/AP-1 signal pathway, i.e. IFNγ and MMPs, which are of importance for an inflammatory state in atherosclerosis in general and for arterial remodeling, important in HT." (PMID 22141572, 2011). "The reduced expression of IL-18 in epididymal WAT is of special interest, since ApoE−/− IL-18−/− mice develop less atherosclerosis than control ApoE−/− mice." (PMID 21042583, 2010). "Interestingly, ZL effectively alleviates vascular endothelial cells in atherosclerosis by regulating the miR-30b-5p/NLRP3 axis and significantly reduces the AS-related mRNA expression levels of NLRP3, ASC, Caspase 1, IL-1 β, and IL-18." (PMID 40373162, 2025). "IL-18 enhances the expression of adhesion molecules such as E-selectin, ICAM-1, and VCAM-1, and augments the secretion of inflammatory mediators like IL-6 and CRP, thereby worsening atherosclerosis and myocardial injury." (PMID 41194915, 2025). "In mouse models of atherosclerosis, S1PR2 signaling in activated macrophages was shown to promote production of proinflammatory cytokines (e.g., IL-1β, IL-18), and S1PR2 may retain macrophages in atherosclerotic plaques." (PMID 39854311, 2025).
atherosclerosis (continued). "This induces the expression of pro-inflammatory cytokines (IL-1, IL-6, IL-8, IL-12, and TNF-α), adhesion molecules, and chemokines (MCP-1, IL-18, and RANTES), driving atherosclerosis via EC dysfunction, leukocyte infiltration, and SMC migration and proliferation." (PMID 39113913, 2024). "Although previous studies have examined the role of IL-18 and GSDMD in the destruction of periodontal tissue and in atherosclerosis, data is scarce regarding the salivary levels of IL-1β, IL-18, and GSDMD in patients with periodontitis, with and without CHD." (PMID 39071510, 2024). "IL-1β and IL-18, both by-products of NLRP3 inflammasome activation, appear to have a relevant contribution in the occurrence and propagation of atherosclerosis which is corroborated by abundant data obtained from the evaluation of atherosclerotic plaques in rodents and humans." (PMID 37175869, 2023). "Inflammatory modulators/biomarkers, such as IL-1α, IL-1β, IL-6, IL-12, IL-15, IL-18, and tumor necrosis factor α, or alternative anti-inflammatory cytokine IL-10, and adhesion molecules (ICAM-1, VCAM-1), involved in atherosclerosis progression have been shown to predict cardiovascular diseases." (PMID 37374202, 2023). "We then analyzed the level of IL-1β, IL-18, TNF-α and NF-κB p65 in arteries of atherosclerosis." (PMID 36759876, 2023). "Our previous results confirmed that IL-18 and IFN-γ play a key role in atherosclerosis." (PMID 35204237, 2022). "So far, the relationship between atherosclerosis, blood lipids, glucose, joint inflammation, and IL-18 seems to be complex and not entirely clear." (PMID 35160217, 2022). "In a recent study, IL-18 was shown to repress TRAIL expression in monocytes/macrophages leading to a blockade in reverse cholesterol transport and exacerbation of inflammation and atherosclerosis." (PMID 33936102, 2021). "Although there is no doubt that there exists a close relationship between IL-18 and accelerated atherosclerosis in CKD, only in a few studies was this cytokine evaluated among patients suffering from CKD." (PMID 32823917, 2020). "IL-1β, IL-6, IL-18, c-reactive protein (CPR), tumor necrosis factor α (TNF-α), etc., as important proinflammatory factors in the process of atherosclerosis, play an important role in promoting the formation of atherosclerosis." (PMID 32733941, 2020). "Among the cytokines secreted by Th1 cells, IL-18 appears to negatively regulate VSMC accumulation within atheroma lesions in ApoE−/− mice, supporting the notion that IL-18 is an important mediator of Th1-induced atherosclerosis." (PMID 31824304, 2019). "IL-18 is known to be an interferon (IFN)-γ-inducible factor with strong activity on macrophages and T cells, which play a crucial role in the occurrence and development of atherosclerosis." (PMID 31354731, 2019). "To determine whether liquefaction of the brain following stroke shares other characteristics with atherosclerosis we measured the levels of OPN, IL-18, MMP-2, MMP-3, and MMP-8." (PMID 30417081, 2018). "IL-18, as a member of IL-1 family, is regulated by the activation of NLRP3 inflammasome and has been proved to play a pro-inflammatory role in the pathogenesis of atherosclerosis." (PMID 28950870, 2017). "Per os administration of colchicine did not influence atherosclerosis progression in cholesterol-fed rabbits, levels of IL-18, insulin and leptin." (PMID 28950870, 2017). "IL-12 and IL-18 stimulate TH1 cells to produce interferon-γ, which promotes atherosclerosis by activation of macrophages, inducing production of pro-inflammatory mediators, and increasing smooth muscle cell proliferation, collagen production, and matrix metalloproteinase (MMP) activity." (PMID 25699211, 2015). "The included studies used different blood-derived markers of atherosclerosis, such as: high sensitivity CRP (hsCRP), vasogenic endothelial growth factor (VEGF), interleukins (IL) IL-6 and IL-18, osteopontin (OPN), osteoprotegerin (OPG) and tumor necrosis factor-alpha (TNF-α)." (PMID 25984600, 2015).
atherosclerosis (continued). "Interleukin 18 (IL-18), previously known as interferon-gamma (IFN-γ) inducing factor, is a proinflammatory member of IL-1 superfamily which plays a role in the initiation and progression of atherosclerosis." (PMID 24307760, 2013). "Moreover, other studies had shown a correlation between PCOS and serum markers of atherosclerosis such as CRP, interleukin-18, homocysteine, and endothelial dysfunction." (PMID 21062435, 2010). "In addition, GCF levels of IL-18 had a predictive value for the development of subclinical atherosclerosis, a finding that was not previously published." (PMID 36983201, 2023). "In addition, it was recently shown that both IL-18 and Na-Cl co-transporter (NCC) are necessary to coordinate the IL-18R cell signaling in atherosclerosis, rising a novel pathway for signaling in atherogenesis and plaque vulnerability involving the IL-18/IL-18R dyad." (PMID 36613465, 2022). "Moreover, dapagliflozin inhibited the expression of NLRP3, ASC, caspase-1, IL-1β, and IL-18 in DM mice, and such expression was also decreased in the nondiabetic atherosclerosis model (not statistically significant)." (PMID 28104929, 2016). "However, the overall effects of dapagliflozin on atherosclerosis in DM and the potential benefits involved, for example, their effects on IL-1β and IL-18 cytokines and NLRP3 inflammasome systems, have not been evaluated." (PMID 28104929, 2016). "Although IL-18 is not currently considered a useful tool for the presence of subclinical atherosclerosis in general population, the AtheroGene Study indicates that high serum concentrations of IL-18 likely cause cardiovascular death in patients with coronary artery disease." (PMID 22577254, 2012). "IL-10 was undetectable in all patients, regardless of the presence of atherosclerosis, and IL-18 was positive in only one patient (1.8%) who presented with MASLD, no atherosclerosis, and normal bilateral CIMT." (PMID 40299570, 2025). "Interestingly, even though TLR4 deficiency reduced atherosclerosis extent, the lack of MyD88, an adaptor protein in the TLR signaling cascade, further reduced it, possibly because it participates in the signal-transduction pathway of the receptors for IL-1β and IL-18." (PMID 30558209, 2018).